EGFR (epidermal growth factor receptor)
Diseases named in the same sentence as EGFR in open-access papers (continued):
Sharing a sentence is not in itself a finding about the gene and the disease.
tumor (continued). "Progesterone Receptor Membrane Component 1 (PGRMC1/Sigma-2 receptor) is located on chromosome Xq21 and encodes a haem-containing protein that interacts with epidermal growth factor receptor (EGFR) and cytochromes P450, with function in tumor proliferation and chemoresistance." (PMID 31970154, 2019). "Among the EGFR wild-type patients, 12 had KRAS mutations in their tumours." (PMID 30953094, 2019). "This analysis confirmed the overexpression of EGFR in both tumor and suppressed tumor discs." (PMID 31568500, 2019). "In this scenario, one would expect to find other genetic fingerprints of the tumor in cfDNA despite not being able to detect EGFR mutations in the plasma sample." (PMID 31861832, 2019). "Based on this evidence, platinum-based chemotherapy plus PD-1/PD-L1 inhibitor is strongly recommended in patients with PS 0–1, whose tumor is positive for PD-L1 ≥ 50%, and who do not have EGFR mutation or ALK rearrangement." (PMID 31049758, 2019). "Studies have shown that PD-L1 expression can be induced by extrinsic stimulation such as interferon-gamma produced by surrounding tumor cells, and by the activation of intrinsic oncogenic pathways, such as STAT3, an activating EGFR mutation or ALK translocation." (PMID 30961670, 2019). "The fact that the original tumor was EGFR and KRAS wt classified it for second line EGFR treatment." (PMID 31323891, 2019). "(2013) have suggested that these mutations only occur after treatment with cetuximab, as evidenced by their study of 505 patients, in which mutations in tumor tissue were detected after anti‐EGFR therapy but not before." (PMID 31350822, 2019). "Altogether, the results presented here suggest that IL-1α in combination with cetuximab can induce a T cell-dependent anti-tumor immune response and may represent a novel immunotherapeutic strategy for EGFR-positive HNSCCs." (PMID 30890189, 2019). "It suggests that the low response rate to LR004 in the ESCC KYSE520 tumor model might be due to high frequency of gene alteration of EGFR downstream signaling pathways." (PMID 30372581, 2019). "Subgroup analysis indicated that this epigenetic signature could distinguish high and low-risk patients also in different molecular or histological tumour subtypes (by Her2-, EGFR- or ER expression or different tumour grades)." (PMID 31747912, 2019). "Given its role in promoting cell cycle progression, it is conceivable that increased EGFR levels mediate an increase in tumor repopulation between fractions; a radiotherapy response determining process that is counteracted by radiotherapy treatment acceleration or concurrent chemotherapy." (PMID 31998639, 2019). "Initial analysis demonstrated that increase of lysosomal acidification could enhance or sensitize tumor cell response to an EGFR inhibitor, potentially providing a strategy for targeted cancer therapy." (PMID 31717697, 2019). "Moreover, EGFR was found to be significantly upregulated in tumor samples compared to normal samples, as shown in 10 of the 23 HNC datasets collected in HNCDB." (PMID 31139565, 2019). "This indicates that EGFR-TKIs may reduce pERK and inhibit tumor cell proliferation partially through downregulation of CXCR7." (PMID 30935067, 2019). "Inversely, inhibition of autophagy overcame the resistance of tumor cells to EGFR-TKIs." (PMID 31811814, 2019). "However, only limited data are available regarding the implication of the long-term application of anti-EGFR biologicals on the structure and function of NK cells as well as their interaction with tumor cells." (PMID 31546690, 2019).
tumor (continued). "EGFR inhibitors were used to treat those tumor-bearing mice and we observed that Erlo, Gefi and Lapa restrained the tumor growth and prolonged the tumor-bearing mice survival time in total and integrin αvβ3− A549 tumors while the mice bearing αvβ3+ A549 tumor revealed significant drug resistance." (PMID 31316001, 2019). "Second, we analyze how systemic treatment of CRC might result in altered tumor microenvironment and acquired resistance to anti-EGFR therapy." (PMID 31370270, 2019). "In addition, 1 tumour had very high expression of EGFR (7635 amol/μg) and 4 harboured high expression levels of HER2 (confirmed by standard IHC)." (PMID 31537838, 2019). "A large body of evidence supports the ability of EGFR status to predict tumor radioresponsiveness." (PMID 31349558, 2019). "EGFR also plays an important role in cell derivatization; the interrelated study has revealed that EGFR offered significance contribution in the cancer development process, such as metastasis of tumor cells, adhesion, apoptosis, and angiogenesis." (PMID 30906412, 2019). "EGFR transduction is complex, and tumor cells can avoid effects of cetuximab." (PMID 31717302, 2019). "Therefore, we systematically evaluated the anti-tumor activity of PCC0208027 in NSCLC tumors with drug-sensitive or -resistant EGFR mutations, and HER2 amplification, and elucidated its potential anti-tumor mechanisms." (PMID 30952931, 2019). "Furthermore, the prognostic value of membrane-bound, cytoplasmic (mcEGFR) and nuclear expression (nEGFR) of EGFR was experimentally analyzed by immunohistochemical staining of 502 biopsies from 27 tumor types." (PMID 30956774, 2019). "We conducted a retrospective analysis to evaluate the effect of tumor location on prognosis and efficacy of biological agents (anti-EGFR, Cetuximab and Panitumumab, or anti-VEGF, Bevacizumab) added to first-line chemotherapy in patients with RAS wild-type (wt) mCC." (PMID 31762802, 2019). "Our results suggest that genetic modification of CD8+ T cells to express EGFR might be considered in immunotherapeutic strategies based on adoptive transfer of anti-tumor T cells against cancers expressing EGFR ligands." (PMID 31921216, 2019). "We develop a 3D multiscale model to explore the role of EGFR overexpression on tumour initiation." (PMID 31016574, 2019). "The latest findings strongly suggest that complex molecular alterations coupled with changes of the immune tumor microenvironment may substantially contribute to the clinical efficacy of EGFR antagonist." (PMID 31370270, 2019). "The extracellular domain of EGFR may therefore be an ideal tumor-specific epitope for TNBC therapies." (PMID 31804974, 2019). "In our previous study, clinically, JX-594 demonstrated tumor selectivity via viral thymidine kinase (vTK) inactivation because cancer cells have high cellular TK levels due to Epidermal growth factor receptor (EGFR) pathway activation, in which the VV was evolved to replicate selectively in tumors." (PMID 31717883, 2019). "Thus, PKCι-PAK1 signaling is an important pathway in tumor genesis in EGFR mutant, KRAS mutant and SCC cell lines." (PMID 31660987, 2019). "Two independent studies also revealed EGFR-mutated-positive NSCLC had a unique metabotype according to lipidomic profiling in lung pleural effusion and phospholipids of tumor extracellular vesicles were different in gefitinib-resistant NSCLC cells from gefitinib-sensitive NSCLC cells." (PMID 31555581, 2019). "Furthermore, combination of JQ1 with EGFR inhibitor significantly reduced 97-H tumor growth in vivo, along with decreased level of p-MYC-Ser62." (PMID 30770740, 2019).
tumor (continued). "In conclusion, our findings demonstrated that patients with EGFR mutations poorly responded to nivolumab treatment regardless of PD-L1 expression on tumor cells." (PMID 30978241, 2019). "Patient CRUK0056 was not a candidate to receive targeted therapies since her tumour was classified as stage IB and she did not harbour any mutation associated to known driver genes (e.g., EGFR, ALK, ROS1, BRAF, RET)." (PMID 31540260, 2019). "Thus, in place of the pathway on which the tumor is dependent, tumor cells increase expression and activity of RTKs, such as EGFR, MET, and FGFR, by cytokines and growth factors in the tumor microenvironment to escape tumor therapy." (PMID 30717262, 2019). "Other pathologic and molecular tumor biomarkers, such as epidermal growth factor receptor (EGFR) amplification, aldehyde dehydrogenase 1A3 (ALDH1A3), and isocitrate dehydrogenase (IDH1/IDH2) isoforms are current foci of research and have been linked to prognosis." (PMID 31882968, 2019). "Furthermore, a significant correlation between high EGFR activity in tumor cells and macrophage-tumor cell proximity was found to partially account for the intratumoral heterogeneity in EGFR activity observed in CRC." (PMID 31370270, 2019). "Furthermore, analyses of hub genes' prognostic roles demonstrated significant oncogenic effect of EGFR and tumor suppressive effect of PPP3CB and MYO5A in GBM." (PMID 30971889, 2019). "Hence, EGFR is well known as a prognostic tumor marker and therapeutic target in different tumor entities." (PMID 31438847, 2019). "About 100 EGFR gene mutations traditionally have been detected by tissue sample from primary tumor site, but tumoral tissue biopsy is not always feasible especially in patients with poor performance." (PMID 31870098, 2019). "The selective inhibition of endocytosis could also prove useful in combination with cancer therapies, which exploit the antibody-based recognition of surface-localized tumor markers such as EGFR for the delivery of cytotoxic drugs." (PMID 31671891, 2019). "Altogether, we believe we have identified a combined high nuclear IL-1α/EGFR+ tumor expression profile as a strong prognostic biomarker for progression-free survival in OSCC patients which warrants further study in other HNSCCs and other EGFR-expressing tumors." (PMID 31320902, 2019). "In conclusion, apatinib combined with chemotherapeutic agent or EGFR‐TKI can improve anti‐tumor activity, which may have the potential of delaying drug resistance and prolonging the survival time of NSCLC patients." (PMID 31486270, 2019). "Levels of EGFR and its downstream signaling are positively correlated with levels of hypoxia in both murine and human tumor tissues, suggesting that hypoxic tumors experience prolonged and enhanced signaling, allowing the tumor cells to survive and maintain homeostasis under stress." (PMID 31717697, 2019). "Our in vitro experiments using antigen specific CD8+ T cells suggest that expression of EGFR on T cells might give a functional advantage in a tumor microenvironment containing EGFR ligands." (PMID 31921216, 2019). "This suggested that tumor resistance related to overexpression of ABCG2 could possibly be overcome by administering EGFR TKIs in combination with anticancer agents that are ABCG2 substrates." (PMID 31340525, 2019). "Interestingly the level of ERBB2 mRNA in the ascites of mice treated with EGFR inhibitor lapatinib was at least twice as high as in the patient's tumor." (PMID 30499260, 2019). "Similarly, a consistently decreased EGFR expression was seen across a range of tumor cell lines when grown in 3D versus 2D43." (PMID 31811202, 2019). "Epidermal growth factor receptor (EGFR) is also known to be overexpressed on tumour cell membranes." (PMID 31137744, 2019).
tumor (continued). "However, we and other groups described that some RAS wt mCRC patients with clinical resistance to anti-EGFR agents had a liquid biopsy positive for KRAS mutations and carried the same variant at very low allelic frequency in the primary tumor." (PMID 31226844, 2019). "Indeed, in accordance with the in vitro data, LRIG1 displayed a decreased expression in patient derived xenograft that proved to be resistant to EGFR blockade (tumor volume increase of at least 35% compared to the initial pre-treatment volume)." (PMID 31052457, 2019). "In addition, high EGFR expression sustains tumor cell repopulation between radiotherapy fractions, as a consequence of the activation of several downstream intracellular effectors mediating cell proliferation and angiogenesis." (PMID 30652016, 2019). "The search of EGFR T790M mutation in ctDNA rather than in tumor tissue DNA is becoming a reliable alternative procedure." (PMID 31029076, 2019). "We extracted total RNA from the plasma of 66 non-squamous NSCLC patients (31 of whom had tumours with EGFR mutations) and measured circulating miRNA levels using quantitative reverse transcription polymerase chain reaction (RT-qPCR)." (PMID 30953094, 2019). "Using anti-human EGFR (clone Hu1) to identify MDA-MB-231 cancer cells within mouse tumor masses after an enzymatic digestion, we analyzed FRα protein expression (clone LK26) in three tumors recovered from mice on FA-replete diet that experienced a relapse despite continuing EC17 treatment." (PMID 30941303, 2019). "Taken together, the data above indicate that the presence of IL-35 in the tumour cell microenvironment might influence the balance between EGFR and PD-L1 under metabolic restriction present in the tumour milieu of NSCLC." (PMID 30956278, 2019). "Globally, genes in post-NAC samples were involved in pathways associated with actionable targets in tumor treatment where, beside the canonical PI3K/Akt/mTOR, EGFR, and Ras signaling pathways the most represented terms were related to regulation of cell cycle processes." (PMID 31717320, 2019). "First-generation EGFR inhibitors (e.g., gefitinib and erlotinib) have shown increased objective response (ORRs) and progression-free survival (PFS) compared to conventional cytotoxic treatment of patients suffering from EGFR-mutated tumours." (PMID 31795465, 2019). "This differential sensitivity between wild-type and mutant receptors, combined with the increased dependency of tumor cells on EGFR signaling, provides the wide therapeutic window that makes EGFR inhibitor therapy much more effective in patients with classical activating EGFR mutations." (PMID 30854234, 2019). "Specifically, cetuximab's stimulation of ADCC and other immunostimulatory activities (DC maturation, T-cell recruitment to the tumor, increased antigen presentation, and cytotoxic T-cell priming) are dependent on cetuximab's simultaneous binding of the EGFR and the CD16 receptor on NK cells." (PMID 31616627, 2019). "Moreover, tumor cells can evade the immune system or promote their own growth through increased EGFR expression and indoleamine 2,3-dioxygenase 1 or VEGF production." (PMID 31331053, 2019). "We hypothesized that imaging with EGFR-specific radioligands may facilitate noninvasive measurement of EGFR expression across the entire tumor burden and allow for dynamic monitoring of cetuximab-mediated changes in receptor expression." (PMID 30213849, 2019). "We thus did not rely on affinity tuning, and instead took advantage of the unique conformational properties of EGFR to ensure tumor specificity, as EGFR806-CAR binding is restricted to tumor-associated conformational states of the extracellular domains of EGFR." (PMID 31903167, 2019). "However, there was no observed advantage of the high drug ratio nimotuzumab-PEG6-DM1-High in vivo likely due to a combination of decreased affinity for EGFR and lower tumor uptake in vivo." (PMID 30800216, 2019).
tumor (continued). "However, further studies using additional GBM PDX models demonstrated that tumours overexpressing EGFR were only sensitive to erlotinib if they also expressed PTEN." (PMID 31616641, 2019). "As the observed incidence of EGFR mutations was only 2.7% in patients with LSCC, EGFR mutations were not applicable to routine testing of all LSCC tumor specimens." (PMID 30643941, 2019). "For EGF transport role, blocking EGF/EGFR signalling pathway to reduce PD-L1 transport in CSCs may be an alternative strategy to enhance anti-tumour immune response." (PMID 30770752, 2019). "On the other hand, in the ALK1174L mutated tumor, PD-L1 expression was not influenced by the anti-EGFR drug, gefitinib." (PMID 31480495, 2019). "Blocking STAT3 could result in synergistic anti-tumor effects in combination with inhibition of EGFR or other tumorigenic dysregulated transcription factors." (PMID 31671769, 2019). "Moreover, a number of EGFR TKI-resistant tumours lack known resistance mechanisms, suggesting the existence of previously unrecognized mediators of EGFR TKI efficacy." (PMID 31741433, 2019). "Functionally, dual blockade of both tumor (EGFR signaling) and the endothelial cells (VEGFR signaling) that support tumor growth may ultimately make a difference in the effectiveness of cancer treatment." (PMID 31699150, 2019). "Poor overall survival is associated with increased tumor volume (HR = 2.12, p = 0.00054), EMT score (HR = 2.15, p = 0.002), DNA CL repair defect (HR = 1.97, p = 0.0043), acute hypoxia (HR = 1.62, p = 0.023) and EGFR expression (HR = 1.68, p = 0.014)." (PMID 31998639, 2019). "Therefore, the expression of EGFR by myeloid cells of the colorectal tumor stroma, rather than the cancer cells themselves, also contributes to tumor development." (PMID 31370270, 2019). "In particular, our findings of overexpressed CD47 in transcriptomic analysis of patients with EGFR-mutated NSCLC, as well as in tumor cell lines acquiring EGFR TKI resistance, identify CD47 as target to be further explored for the immunotherapy treatment of naïve and resistant EGFR-mutant NSCLCs." (PMID 32082304, 2019). "Despite partial activation of EGFR in keratinocytes, aprepitant also demonstrated dose-dependent cytotoxicity to epithelial cells in our study that was consistent with previous reports of its anti-tumor effects." (PMID 31835310, 2019). "EGFR mutation detection in exosomes showed great consistency when compared with gene detection in tumor tissues and cell blocks, and may have important practical value in predicting the treatment response to EGFR-TKI." (PMID 31608233, 2019). "One proposed way to enhance the effect of EGFR inhibition is to combine anti-EGFR mAbs and TKIs, which seems to have a synergistic effect and could result in a stronger anti-tumor effect." (PMID 31443516, 2019). "Furthermore, recent studies have demonstrated that the activation of EGFR modulates not only the intracellular pathways involved in tumor cell survival of many cancer types, but also the host antitumor immunity, by driving PD-L1 expression." (PMID 31470510, 2019). "We could detect high expression of EGFR at the plasma membrane of the tumor cells, as is common for platinum-resistant ovarian cancer." (PMID 30820473, 2019). "Of the 46 EGFR-mutated NSCLC tumor specimens for the first- and second-generation EGFR-TKIs, high, intermediate, low, and no AXL expression was observed in 12 (26.1%), eight (17.4%), 23 (50.0%), and three (6.5%) specimens, respectively." (PMID 30651547, 2019). "Treatment of NSG mice carrying orthotopic GB xenografts expressing wildtype EGFR or EGFRvIII by repeated intracranial injection of CAR-engineered NK-92 cells inhibited tumor growth more strongly than treatment with NK-92 control cells and improved overall survival of the animals." (PMID 31798595, 2019).